IL6 (interleukin 6)
Diseases named in the same sentence as IL6 in open-access papers (continued):
Sharing a sentence is not in itself a finding about the gene and the disease.
COVID-19 (continued). "From the biological parameter’s standpoint, COVID-19 associated with anemia had five times the higher likelihood that SARS-CoV-2 infection alone (reference group), followed by the association with elevated CRP (HR = 3.8) and elevated IL-6 (HR = 2.9)." (PMID 36579593, 2022). "Also, IL-6 has been used as a therapeutic target, and IL-6-blocking antibodies have been widely used to treat COVID-19 patients." (PMID 35663992, 2022). "Our analysis suggests that inflammatory markers such as the IL-6, CRP and IL-6/Ly ratio could potentially be used as predictors of in-hospital mortality for critical COVID-19 patients." (PMID 36142336, 2022). "In parallel, for the sepsis parameters, serum TNF-α, IL-1β, IL-6, IL-8, endotoxemia, and blood-bacteria-free DNA in severe cases were higher than other groups and most of the levels of these parameters were different between COVID-19 severities." (PMID 35406667, 2022). "Moreover, it is intriguing to see elevated levels of OSM, similar to IL-6 and TNFα, in the plasma of COVID-19 patients showing severe symptoms and those who were admitted to the intensive critical unit (ICU)." (PMID 35163735, 2022). "Older patients with severe COVID-19 usually have higher levels of serum IL-6 and IgG antibodies." (PMID 35248063, 2022). "IL-6 is one of the cytokines released during COVID-19-mediated cytokine storm." (PMID 36366543, 2022). "We report the first case of COVID-19 associated acute necrotizing encephalopathy (ANE) without pulmonary disease in a patient with an extremely high interleukin-6 (IL-6) level and Ran Binding Protein 2 (RANBP2) mutation." (PMID 35870896, 2022). "A strength of this research is that it provides scientific evidence indicating that comorbidities such as obesity, T2DM, and hypertension, as well as elevated levels of glucose, IL-6, LDH and CRP are associated with the COVID-19 severity among ICU-admitted patients." (PMID 35464048, 2022). "It has been shown that the antimalarial drug hydroxychloroquine (Plaquenil) inhibits the expression of toll-like receptors (TLRs) and the production of IL-6, and hence may have an anti-COVID-19 impact." (PMID 36506506, 2022). "Therefore, life-threatening bacterial ARDS and COVID-19 ARDS had normal-to-elevated neutrophil counts, similar IL-6 levels and less organ failure as indicated by serum creatinine levels, all of which have been proposed as markers of COVID-19 severity." (PMID 34782790, 2022). "The IL-6-JAK-STAT3 axis is activated in COVID-19 and regulates a myriad of cellular functions." (PMID 35991665, 2022). "In this study, we aimed to use a combination of an LFA technique-based IL-6 test strip and a sensitivity-enhanced spectrometric reader for early recognition of COVID-19 patients who may develop respiratory failure." (PMID 35242747, 2022). "Additionally, pGSN levels combined with plasma IL-6, IP-10 and M-CSF significantly distinguished COVID-19 patients from healthy individuals." (PMID 36148234, 2022). "Therefore, inhibition of IL-6 was proposed as a potential therapeutic target when treating patients with COVID-19." (PMID 35930528, 2022). "IL-6 levels were found to be strongly correlated with mortality of COVID-19 patients." (PMID 35822078, 2022). "One-third of those with mild COVID-19 had elevated IL-6 levels, which may contribute to dysglycemia in these patients." (PMID 35729170, 2022). "Furthermore, randomized trials with anti-IL6 treatments in COVID-19 returned mixed results in terms of clinical benefit with these interventions." (PMID 36422642, 2022). "Tocilizumab, an IL-6 monoclonal antibody, has been administered to COVID-19 patients." (PMID 35336888, 2022). "However metformin has been found to reduce TNF-alpha, IL-6, and possibly boost IL-10 in females more than males, which is relevant to the pathophysiology of COVID-19." (PMID 36395143, 2022).
COVID-19 (continued). "A study had proven that elevated levels of IL-6 could predict the use of invasive mechanical ventilation in patients with severe COVID-19 after administration of Tocilizumab." (PMID 35799791, 2022). "Many studies have documented an increase in IL-6 levels in patients with COVID-19." (PMID 35736649, 2022). "Similarly to our findings, a smaller single center retrospective study reported that COVID-19+ patients were less likely treated with IL6-inhibitors." (PMID 35770002, 2022). "Plasma taken from patients infected with COVID-19 was found to be higher in interleukin-6 (IL-6)." (PMID 36260622, 2022). "Interleukin-6 (IL-6) is one of the most widely explored cytokines in COVID-19." (PMID 35806986, 2022). "Indeed, we observed a differential inflammation status among COVID-19 patients as also exemplified by significant differences in the levels of IL-6 and CRP." (PMID 36377893, 2022). "IL-6 is also the main mediator in patients with COVID-19 with severe respiratory complications." (PMID 36447262, 2022). "The effect of IL-6 on the disease course is presently indistinct; whether its elevation is detrimental or beneficial for COVID-19 is controversial." (PMID 35530861, 2022). "We examined whether TNF receptors (TNFRs: TNFR1, TNFR2) and progranulin (PGRN) levels, in addition to interleukin 6 (IL-6) and C-reactive protein (CRP), are associated with mortality or disease severity in COVID-19 patients." (PMID 36219652, 2022). "In conclusion, we observed that oral selenium supplementation could boost the response of SARS-CoV-2 anti-spike IgG antibodies, IL-6, and IL-10 following the immunization with the Janssen COVID-19 vaccine in BALB/c models." (PMID 36679902, 2022). "LNT, on the other hand, has strong regulatory effects on IL-1β and IL-6, and some researchers have postulated that it may also regulate COVID-19." (PMID 35669119, 2022). "In addition, similarly to our findings, CRP, IL-6, ferritin, D-dimer, LDH, and troponin have been identified as severity and prognostic markers of COVID-19-associated MIS." (PMID 35935801, 2022). "In addition to clinical ones, laboratory evidence must be presented, and it includes elevation of at least two inflammatory markers (CRP, procalcitonin, ESR, ferritin, IL6), and positive COVID-19 PCR or serology tests." (PMID 35494997, 2022). "Previous studies suggest that both OSA and COVID-19 increase the expression of several inflammatory stress, including proinflammatory cytokines as IL-6, developing an endothelial vulnerability, and therefore, increasing the permeability of this markers to the brain." (PMID 35775008, 2022). "Furthermore, DM is a proinflammatory condition defined by an incorrect and excessive cytokine reaction, as demonstrated in COVID-19 subjects, where blood counts of IL-6, CRP, and ferritin were considerably greater in DM patients." (PMID 35165505, 2022). "Intriguingly, Multivariate ANOVA with Bonferroni’s multiple testing revealed the significant reduction in the protein expression level of IL-6 in patients that received COVID-19 treatments (e.g., tocilizumab, lopinavir/ritonavir, favipiravir) in comparison to untreated patients." (PMID 35529862, 2022). "Thus, we tested the effect of NSP5, NSP9, and NSP10 on the expression of IFNβ, IL-6, and IL-1β, which are some of the most frequently deregulated cytokines in COVID-19 patients." (PMID 36173315, 2022). "In a previous work, we showed that IL6 could be a severity biomarker but also a guide to select COVID-19 patients who could benefit from treatment with tocilizumab, an inhibitor of the IL6 receptor." (PMID 35783606, 2022). "ACE2, IL-6, ORF1ab, and ORF3a are miRNA-related therapeutic targets for COVID-19 treatment." (PMID 36204652, 2022). "Mice treated with CEP suppress inflammatory response by reducing the levels of TNFα, IL-1β, and IL-6, suggesting CEP may be useful for controlling the cytokine storm associated with COVID-19." (PMID 36278757, 2022).
COVID-19 (continued). "The so-called “cytokine storm” was present only in patients with chimeric antigen receptor (CAR) T cell-induced cytokine release syndrome—CRS—and the pooled mean IL-6 serum concentration was 3110.5 pg/mL, nearly 100-fold higher than in the severe and critical COVID-19 patient populations." (PMID 36289881, 2022). "A large-scale meta-analysis enrolling more than 13,000 participants has shown that the serum level of cytokines (i.e., IL-6) could be a potential indicator of disease severity as well as mortality for those diagnosed with COVID-19." (PMID 35885582, 2022). "In COVID-19 patients, IL6 was markedly overexpressed and attributed to inflammation." (PMID 35992697, 2022). "Namely, evidence has revealed that severe COVID-19 patients admitted to intensive care units (ICUs) show elevated levels of pro-inflammatory mediators such as IL-1, IL-2, IL-6, IL-7 IFN- γ, and TNF-α and reduced lymphocyte counts when compared to non-ICU patients." (PMID 35645219, 2022). "Accordingly, blockers of both IL-1 and IL-6 have been investigated in treatment of COVID-19." (PMID 36422492, 2022). "COVID-19-induced reduction of IL-6 in an inflammatory state may have a hitherto undiscovered therapeutic impact." (PMID 36506506, 2022). "Interestingly, many lncRNAs which are differentially expressed in COVID-19 patients’ BALF were heavily involved in lncRNA-mediated regulation of IL-6." (PMID 36052163, 2022). "Next, we investigated more deeply the interplay between IFNs and immune markers whose elevation in circulation has been associated with poor prognosis in COVID-19, including interlelukin (IL)-22, SAA, IL-10, IP-10, IL-6, IL-8, MIP-3α, IL-1RA, MIP-1α, TNF-α, MCP-1, and MCP-4 (39, 40, 43, –45)." (PMID 35217532, 2022). "However, plasma IL-6 levels in severe COVID-19 patients are much lower than those in cytokine release syndromes due to immunotherapy." (PMID 35359837, 2022). "This was noted in conjunction with IL-6, another well-established marker of mortality in COVID-19." (PMID 35259186, 2022). "In COVID-19, IL-6 and CRP showed the highest prognostic value in the univariable model." (PMID 35622838, 2022). "Elevated IL-6 serum levels in COVID-19 patients may be a sign of cytokine release syndrome, suggesting that controlling IL-6 could decrease the natural course of the disease." (PMID 35359702, 2022). "It was previously shown that the lower levels of IFN-α in the blood of seriously ill COVID-19 patients could be accompanied by elevated levels of pro-inflammatory cytokines (IL-5, IL-6, IL-10, and IL-13)." (PMID 36014561, 2022). "Drugs adopted for in-hospital treatment of COVID-19, especially anti-IL6 and small molecules, could impact significantly on FMD function after discharge, and specific studies should be performed to address this point." (PMID 35407382, 2022). "Laboratory markers including interleukin 6 (IL-6), C-reactive protein (CRP), ferritin, platelets, lactate dehydrogenase (LDH), erythrocyte sedimentation rate (ESR), D-dimer and lymphopenia are significantly implicated in COVID-19 complications." (PMID 36148234, 2022). "Using sera derived from patients suffering from COVID-19, we could demonstrate that the eGC became progressively worse in relation to disease severity (mild vs severe course) and in correlation to IL-6 levels." (PMID 35867189, 2022). "Elevated IL-6 level in COVID-19 patients is a predictor of higher mortality rates." (PMID 36499222, 2022). "With COVID-19 patients known to manifest neurological symptoms and NLRP3 known to be implicated in neurological diseases like Alzheimer’s —blocking IL-1 can conceivably be more efficacious than IL-6 in managing COVID-19." (PMID 35431536, 2022). "It inhibits the intracellular cytokine signaling pathways known to be active in severe COVID-19 and reduces levels of IL-2, IL-6, IL-10, IFN-γ, and granulocyte–macrophage colony-stimulating factor (GM-CSF), some of which are important to the cytolytic T cell response." (PMID 35079694, 2022).
COVID-19 (continued). "Indeed, in the cohort of patients included in this study, a higher proportion of COVID-19 patients with new-onset AF had an acute ischemic stroke at admission, as well as high levels of IL-6 compared to the other groups." (PMID 35454369, 2022). "In the previously published RCT study, the researchers found that patients with COVID-19 receiving lopinavir-ritonavir along with interferon beta-1b and ribavirin had a significantly lower level of IL-6 at days 2, 6, and 8 in comparison with patients who only received lopinavir and ritonavir." (PMID 36091037, 2022). "sTREM-1 and IL-6 also appear to be good predictors of adverse outcome in patients presenting with fever in emergency departments (including those with LRTIs and particularly those with COVID-19)." (PMID 34991507, 2022). "We lastly applied ECLipse to analyze IL-3 and IL-6 in plasma samples of patients with COVID-19." (PMID 36129990, 2022). "Moreover, a substantial increase in the proportion of blood inflammatory monocytes (CD14+CD16+ cells) capable of secreting IL-6 has been reported in COVID-19 patients with severe disease." (PMID 35284964, 2022). "In contrast, patients in the acute COVID-19 group had higher levels of IL-6." (PMID 35846757, 2022). "If the immune response is not controlled in patients with aggravated COVID-19, the levels of cytokines such as IL-6 increase, possibly inducing a cytokine storm and causing serious lung damage and death." (PMID 36018890, 2022). "Moreover, the IL-6 blockers tocilizumab and sarilumab have shown some efficacy in COVID-19, supporting a specific role for IL-6 in the progression of disease." (PMID 35308241, 2022). "It has been suggested that COVID-19 patients show an elevated expression of inflammatory cytokines, such as serum interleukin-10 (IL-10), IL-6, and IL-1β, compared to those with less severe symptoms, indicating the role of cytokine storm in the intensity of disease symptoms." (PMID 35455977, 2022). "Similarly, in 125 COVID-19 patients measured with lymphocyte subsets, the IL-6 levels were significantly increased with increasing disease severity, with the median IL-6 values in critical COVID-19 patients were significant higher than those of mild patients." (PMID 36403042, 2022). "Interestingly, the profile of this cluster in COVID-19 again shows a mixed Th1/Th2/Th9/Th17 response, together with innate cytokines (IL-1β, IL-6), eosinophil chemokines (CCL11), growth factors, and vasoactive molecules (GM-CSF, HGF, EGF, VEGF)." (PMID 35674675, 2022). "Although, IL-6 appears to play a predictive role in the development and outcome of severe COVID-19, along with other biochemical and clinical findings it could serve as an indicator of the disease outcome." (PMID 35530861, 2022). "The efficacy of immune modulatory therapies such as IL inhibitors (IL-1, IL-6), corticosteroids, or convalescent plasma from patients who have already recovered from COVID-19 remains unclear for patients suffering from MIS-C." (PMID 35980407, 2022). "(2021) identified a likely risk of developing prolonged symptoms of COVID-19 in hospitalized patients, noting that convalescent patients had a lower frequency of IL-10+ CD4+ T cells, IL-17+ CD4+ T cells, and IL-6+ B cells, compared to individuals with acute COVID-19." (PMID 35846757, 2022). "The induction of several cytokines like IL-6 and a strong pro-inflammatory response is a classical feature of COVID-19 which may promote cryptic translation due to stress-mediated alteration of the translational machinery." (PMID 35222346, 2022). "The earliest reports of COVID-19 clarified that IL-1β, IL-6, TNFα, and CCL3 in the peripheral blood of patients with severe COVID-19 pneumonia were significantly higher than those of non-severe patients, and this cytokine storm is an important factor contributing to death from COVID-19." (PMID 35120332, 2022). "The most predictable cytokines for COVID-19 and control were IL-6 and IL-12p70." (PMID 35967091, 2022).
COVID-19 (continued). "Ct values were negatively correlated with IL-6 (ORF1a/b p = 0.0458, N p = 0.0426) and IL-8 (ORF1a/b p = 0.0208, N p = 0.0123) concentrations, and positively correlated with eosinophil count (ORF1a/b p = 0.0171, N p = 0.01) in patients with COVID-19." (PMID 36620263, 2022). "This suggest that circulating IL-6 drives CD4 T cell STAT3 activation during acute COVID-19." (PMID 35421120, 2022). "Measuring IL-3 and IL-6 in patients with COVID-19 produced intriguing results." (PMID 36129990, 2022). "A number of studies have shown that the sign of COVID-19 was the cytokine storm with elevated levels of interleukin-6 (IL-6), IL-1β, complement C1r (C1R), tumor necrosis factor-alpha (TNF-α), chemokine (C-C-motif) ligand 2 (CCL2), and granulocyte-macrophage colony-stimulating factor (GM-CSF)." (PMID 35726234, 2022). "IL-6-driven diseases include cytokine-release syndrome following chimeric antigen receptor (CAR) T-cell therapy, giant cell arteritis, and recently SARS-CoV-2 infection (COVID-19), mainly in severe cases associated with adverse clinical outcomes." (PMID 35626318, 2022). "For severe COVID-19 condition, anti-inflammatory intervention such as corticosteroids (dexamethasone), interleukin-6 (IL-6) receptor blockers (tocilizumab), and baricitinib, a Janus kinase inhibitor, have shown to result in clinical improvement and reduce mortality." (PMID 36742008, 2022). "The immunopathology of COVID-19 is characterised by an elevation of IL-6 and TNF-α." (PMID 35843719, 2022). "Importantly, reduced IL-6 levels were also found in COVID-19 patients treated with the FIASMA hydroxyzine." (PMID 34608263, 2022). "Finally, serum proteomics was performed by D’Alessandro and colleagues on 49 subjects, including 16 controls and 33 COVID-19 patients, whose severity status was inferred measuring IL-6 levels." (PMID 35269564, 2022). "This hypothesis is further supported by the results of a recent meta-analysis on the effects of IL-6 inhibitors in COVID-19." (PMID 35208467, 2022). "On ROC analysis, urea was fair (AUC=0.721), creatinine (AUC=0.698) and IL-6 (AUC=0.698) were acceptable predictors of mortality, while albumin (AUC=0.698) was an acceptable predictor of survival in severely ill COVID-19 patients during their intensive care stay." (PMID 36185918, 2022). "Besides, TCM also regulates interleukin-6 (IL-6), a cytokine storm mediator, to improve COVID-19 symptoms." (PMID 36684919, 2022). "Assessment of cytokine levels among patients with acute COVID-19 and individuals in the post-COVID-19 period showed significantly higher levels of IL-17 (p=0.0002), TNF-α (p<0.0001) and IL-2 (p<0.0001) in the post-COVID-19 group and higher levels of IL-6 (p<0.0001) in the acute COVID-19 group." (PMID 35846757, 2022). "Differences between intervention (4sec inhalation, 6sec exhalation for 20 minutes 3x daily) and control group in IL-6 calculated using multilevel mixed-effect linear regression models with random slope including the covariates relevant comorbidities, COVID-19 medication, and age." (PMID 36263035, 2022). "Relatively selective COX-2 inhibitors (e.g., celecoxib, etoricoxib) may reduce pro-inflammatory cytokine levels, as shown in mice with influenza A infection (TNF-α, G-CSF, and IL-6) and in hospitalized COVID-19 patients (IL-6)." (PMID 35530041, 2022). "IL-6 was detected more in dead and symptomatic patients with COVID-19 than in asymptomatic HCWs." (PMID 35336861, 2022). "Therefore, changes in IL-6 and D-dimer can predict worsening in moderate and severe COVID-19 patients." (PMID 37841828, 2022). "Furthermore, the increased levels of IL-6 among COVID-19 patients with severe symptoms correlate with the detection of SARS-CoV-2 nucleic acid in serum." (PMID 35565841, 2022).